AK4P1 (adenylate kinase 4 pseudogene 1)
Synonyms: formerly AK3P1
Gene: Processed pseudogene on chromosome 17 (31,345,519 to 31,346,190, forward strand). Ensembl gene ENSG00000263535.
Diseases named in the same sentence as AK4P1 in open-access papers:
AK4P1 is named in the same sentence as 4 diseases in open-access papers, as found by Europe PMC text mining. Sharing a sentence is not in itself a finding about the gene and the disease. The quoted sentences say what the papers report.
pancreatic adenocarcinoma (1 paper, 2023). "Among these miRNAs, only two miRNAs, involving miR-676-3p and miR-375, were inversely correlated with AK4P1 expression in pancreatic adenocarcinoma." (PMID 36476264, 2023). "Among the three RNAs, only AK4P1 possessed statistical prognostic values (overall survival and disease-free survival) in pancreatic adenocarcinoma." (PMID 36476264, 2023). "Intriguingly, AK4P1 expression was significantly decreased after knockdown of SP1 in pancreatic adenocarcinoma." (PMID 36476264, 2023). "Survival analysis revealed a statistically predictive role of AK4P1 for unfavourable prognosis of patients with pancreatic adenocarcinoma." (PMID 36476264, 2023). "Conclusively, the present study elucidated a key regulatory loop AK4P1/miR-375/SP1 in pancreatic adenocarcinoma." (PMID 36476264, 2023). "Subsequently, we explored the downstream action mechanism of AK4P1/miR-375 in pancreatic adenocarcinoma." (PMID 36476264, 2023). "Intriguingly, expression determination validated that SP1 could positively regulate AK4P1 levels in pancreatic adenocarcinoma." (PMID 36476264, 2023). "Subcellular location analysis indicated that AK4P1 was mainly located in cytoplasm, in which AK4P1 might competitively bind to tumour suppressive miR-375 in pancreatic adenocarcinoma." (PMID 36476264, 2023). "A positive correlation of AK4P1 with AK4 in pancreatic adenocarcinoma was observed." (PMID 36476264, 2023). "Our findings suggested that AK4P1 increased SP1 expression by competitively binding to shared miR-375 and SP1 could conversely positively regulate AK4P1 expression in pancreatic adenocarcinoma." (PMID 36476264, 2023). "Finally, a key regulatory loop AK4P1/miR-375/SP1 was identified in pancreatic adenocarcinoma." (PMID 36476264, 2023). "Finally, AK4P1 might also exert its effects by interacting with oncogenic parental gene AK4 in pancreatic adenocarcinoma." (PMID 36476264, 2023). "Next, stage expression analysis for the 20 RNAs was conducted in pancreatic adenocarcinoma by GEPIA database, and three RNAs (RP11-719K4.3, FER1L4 and AK4P1) were selected for subsequent study." (PMID 36476264, 2023). "Thus, we explored the relationship between AK4P1 and its parental gene AK4 in pancreatic adenocarcinoma." (PMID 36476264, 2023).
pancreatic carcinoma (1 paper, 2023). "In conclusion, the present study elucidated a key regulatory loop AK4P1/miR-375/SP1 in pancreatic carcinoma." (PMID 36476264, 2023). "Moreover, we also demonstrated that AK4P1 might also exert its oncogenic effects through positively regulating AK4 in pancreatic carcinoma." (PMID 36476264, 2023).
tumor (2 papers, 2022 to 2023). "Subsequent analysis demonstrated that a higher level of AK4P1 expression indicated poorer OS and DFS, and was also strongly associated with a worse tumor stage for PDAC patients." (PMID 35220277, 2022). "Moreover, expression analysis of the 5 upregulated DEPs among tumor node metastasis (TNM) stages suggested that only AK4P1 expression possessed statistical difference." (PMID 35220277, 2022).
AK4P1 also shares sentences with these, for which no sentence is quoted: pancreatic ductal adenocarcinoma (1 paper).